ENSG00000206549 (novel protein identical to PRSS50)
Gene: Protein-coding gene on chromosome 3 (46,712,115 to 46,812,574, reverse strand). Ensembl gene ENSG00000206549.
Genetic constraint (gnomAD): Loss-of-function variants: 23 observed, 32.35 expected, observed/expected ratio (o/e) 0.71, 90% interval 0.51 to 1.01. Missense variants: 484 observed, 515.1 expected, observed/expected ratio (o/e) 0.94, 90% interval 0.87 to 1.01. Synonymous variants: 224 observed, 215.91 expected, observed/expected ratio (o/e) 1.04, 90% interval 0.93 to 1.16.